COX14 (cytochrome c oxidase assembly factor COX14)
Description:
Core component of the MITRAC (mitochondrial translation regulation assembly intermediate of cytochrome c oxidase complex) complex, that regulates cytochrome c oxidase assembly. Requires for coordination of the early steps of cytochrome c oxidase assembly with the synthesis of MT-CO1.
Synonyms: C12orf62; MGC14288; MC4DN10; PCAG1
Tractability: Antibody: UniProt predicts a signal peptide or a membrane-spanning region. PROTAC: ubiquitination databases record sites on it; its protein half-life has been measured.
Gene: Protein-coding gene on chromosome 12 (50,112,082 to 50,120,457, forward strand). Ensembl gene ENSG00000178449.
Subcellular location: Mitochondrion outer membrane
Subcellular location (Human Protein Atlas): Mitochondria
Pathways (Reactome):
Metabolism: Complex IV assembly
Gene Ontology:
Molecular function: protein binding; protein folding chaperone
Biological process: mitochondrial respiratory chain complex IV assembly; protein folding
Cellular component: mitochondrial outer membrane; mitochondrion; mitochondrial inner membrane
Genetic constraint (gnomAD): Loss-of-function variants: 3 observed, 6.42 expected, observed/expected ratio (o/e) 0.47, 90% interval 0.21 to 1.2. That is too few expected variants to judge how well the gene tolerates losing a copy. Missense variants: 72 observed, 75.85 expected, observed/expected ratio (o/e) 0.95, 90% interval 0.78 to 1.15. Synonymous variants: 25 observed, 27.8 expected, observed/expected ratio (o/e) 0.9, 90% interval 0.65 to 1.26.
Gene-disease validity (ClinGen):
ClinGen rates the evidence that COX14 causes each of these diseases.
mitochondrial disease (autosomal recessive): Limited.
Homologues: Orthologues: pig COX14 (86% identical), rat Cox14 (82% identical), mouse Cox14 (81% identical), rabbit COX14 (77% identical).
Diseases named in the same sentence as COX14 in open-access papers:
COX14 is named in the same sentence as 8 diseases in open-access papers, as found by Europe PMC text mining. Sharing a sentence is not in itself a finding about the gene and the disease. The quoted sentences say what the papers report.
asthma (2 papers, 2023 to 2025). "Further, a study observed that Sftpc, Nxnl, Lamp3, Gpr 171, and Cox14 genes is associated with asthma and the association is even stronger with atopic and severe asthma." (PMID 40313552, 2025). "We observed that the mild, moderate, and severe asthma subject in the extreme low temperature group showed increased Tob1, Mub2, Sic34a2, Sftpc, Nxnl, Luc71, Lamp3, Gpr171, Cox14, and Cd3e expression, while in the severe asthma subjects showed increased expression in all temperature exposure group." (PMID 40313552, 2025). "Additionally, subjects with severe asthma were more sensitive to low, high temperature and temperature fluctuation conditions, with increased of Tob1, Mub2, Sic34a2, Sftpc, Nxnl, Luc71, Lamp3, Gpr171, Cox14, and Cd3e expression." (PMID 40313552, 2025).
neoplasm (1 paper, 2023). A benign or malignant tissue growth resulting from uncontrolled cell proliferation. "Our study is the first to report about this tumor with unique pathological and molecular features, characterized by a novel rearrangement between COX14 and PTEN genes." (PMID 37312212, 2023). "Whole transcriptome sequencing revealed the presence of a novel genetic rearrangement involving COX14 and PTEN genes, which has never been reported before in any other neoplasm." (PMID 37312212, 2023).
neurodegenerative disease (1 paper, 2018). A disorder of the central nervous system characterized by gradual and progressive loss of neural tissue and neurologic function. "Oxidative phosphorylation genes specific for HCHWA-D, i.e., not represented in the other neurodegenerative disease categories were the ATP6V subunits, COX14, COX15, LRPPRC, and TCIRG1." (PMID 29706885, 2018).
COX14 also shares sentences with these, for which no sentence is quoted: chronic rhinosinusitis (1 paper); diabetes (1); encephalomyopathies (1); liver disease (1); neurological disorders (1).